HDAC1 (histone deacetylase 1)
Diseases named in the same sentence as HDAC1 in open-access papers (continued):
Sharing a sentence is not in itself a finding about the gene and the disease.
allergic rhinitis (2 papers, 2021 to 2022). Inflammation of the nasal mucous membranes caused by an IgE-mediated response to external allergens. "Sodium butyrate restrains the activation of HDAC1 in the antigen specific B cells to induce the expression of IL-10 and decrease the production of IgE in allergic rhinitis model." (PMID 36311721, 2022). "The expression level of HDAC1 in the nasal epithelia is elevated in allergic rhinitis, and HDAC1 inhibitors reduce the symptoms of allergic rhinitis." (PMID 36311721, 2022). "Enhanced IL-4 markedly suppresses the expression of Trek1 via upregulating the expression of the HDAC1 in the nasal mucosa of allergic rhinitis." (PMID 36311721, 2022). "The treatment with antigen-specific immunotherapy and administration of probiotic C. butyricum reduce the serum levels of Th2 cytokines by increasing Trek-1 expression levels and decreasing HDAC1 in the nasal mucosa of allergic rhinitis patients." (PMID 36311721, 2022). "ZO-1 tight junction has an important role in the preservation of epithelial barrier function, while HDAC1 is a common feature of allergic rhinitis." (PMID 34638811, 2021).
alopecia (2 papers, 2013 to 2021). Hair loss usually from the scalp. "Strikingly, deletion of a single Hdac2 allele in HDAC1 knockout mice results in severe epidermal defects, including alopecia, hyperkeratosis, hyperproliferation and spontaneous tumour formation." (PMID 24240174, 2013). "Ablation of histone deacetylase 1/2 (HDAC1/2) function in the developing and adult epidermis leads to several HF defects such as absence of HF formation, expansion of HF bulge region, and alopecia." (PMID 34905545, 2021).
autism (2 papers, 2021). Persistent deficits in social interaction and communication and interaction as well as a markedly restricted repertoire of activity and interest as well as repetitive patterns of behavior. "To identify potential epigenetic aberrations in the VPA-induced autism model, we examined the levels of class I HDACs (HDAC1, HDAC2, HDAC3, and HDAC8) and AcH3 in the PFC nuclear fraction." (PMID 33994921, 2021).
Autoimmunity (2 papers, 2021). The occurrence of an immune reaction against the organism's own cells or tissues. "The transcriptomic profiling and pathway mapping also revealed that autoimmunity-linked, major cell signaling pathways were differentially altered by HDAC1/2 inhibition." (PMID 35222229, 2021). "HDAC1/2 are required for normal T-cell development, and HDAC1 regulates T cell-mediated autoimmunity by regulating CD4+T cells trafficking." (PMID 34880761, 2021).
bladder tumors (2 papers, 2014 to 2019). "Non-invasive (pTa) and pT1 bladder tumours with high expression levels of HDAC-1 showed a tendency towards shorter PFS in our cohort." (PMID 24624923, 2014).
brain cancer (2 papers, 2018 to 2020). A primary or metastatic malignant neoplasm affecting the brain. "Together with the survival-promoting activity of RBBP4, HDAC1 and RBBP4 might cooperate to drive persistent proliferation and growth of tumor cells in RB1 mutant brain cancer." (PMID 29914980, 2018).
carcinoid (2 papers, 2015 to 2019). "However, expression of HDAC1 and HDAC2 were uncoupled in neuroendocrine cell lines, so that in each case one of the isoenzyme transcripts was markedly elevated relative to the other: HDAC2 in SCLC (NCI-H69, NCI-H345 and Lu-165) and HDAC1 in the NCI-H727 carcinoid cell line." (PMID 25970771, 2015).
cardiac arrhythmias (2 papers, 2013 to 2015). Any disturbances of the normal rhythmic beating of the heart or MYOCARDIAL CONTRACTION. "Infection by Moraxella catarrhalis, one of the reasons for exacerbation of chronic obstructive pulmonary disease, induces reduction in the levels of expression and activity of HDAC1 and HDAC2 in bronchial epithelial cells." (PMID 26697414, 2015).
cervical dysplasia (2 papers, 2017 to 2018). "HDAC1 was reported to be more upregulated in cervical dysplasia and carcinoma than in normal cells." (PMID 29312619, 2017).
chondrosarcoma (2 papers, 2017 to 2020). A malignant cartilaginous matrix-producing mesenchymal neoplasm arising from the bone and soft tissue. "HDAC1 and HDAC3 are most abundantly expressed in healthy human cartilage, and we showed that these subtypes are also highly expressed in chondrosarcoma cell lines." (PMID 33266275, 2020).
chronic lymphocytic leukemia (2 papers, 2019 to 2021). "The downregulation of HDAC1 can enhance chronic lymphocytic leukemia cells’ sensitivity to tumor necrosis factor ligand-induced apoptosis." (PMID 34073721, 2021). "Research shows that the downregulation of HDAC1 can enhance the sensitivity of chronic lymphocytic leukemia cells to tumor necrosis factor ligand-induced apoptosis." (PMID 34073721, 2021).
Cirrhosis (2 papers, 2021 to 2023). A chronic disorder of the liver in which liver tissue becomes scarred and is partially replaced by regenerative nodules and fibrotic tissue resulting in loss of liver function. "Interestingly, HDAC1 is expressed in liver tissues from patients with cirrhosis, suggesting a conserved role of Hdac1 from zebrafish to human in LPC differentiation." (PMID 33445518, 2021).
clear cell renal carcinoma (2 papers, 2021 to 2022). A malignant epithelial neoplasm of the kidney characterized by the presence of lipid-containing clear cells within a vascular network. "Immunohistochemical analysis for HDAC-1 on tissue microarray (TMA) specimens of clear-cell renal-cell carcinoma (ccRCC) patients, revealed direct association of HDAC-1 overexpression with positive hypoxia inducible factor (HIF) isoforms (predominantly HIF1a/HIF2a) expression." (PMID 34441281, 2021). "This interpretation is consistent with data showing that CBX4 interacted with HDAC1 to repress the tumor suppressor KLF6 in clear cell renal carcinoma while knockdown of HDAC1 restored KLF6 function." (PMID 35251476, 2022).
coloboma (2 papers, 2018 to 2019). An abnormality in which a part of a structure in one or both eyes is missing. "Coloboma, small eyes, ear and neurogenesis defects are also observed when Hdac1 function is compromised." (PMID 30695021, 2019).
colon adenocarcinoma (2 papers, 2016 to 2021). "To ask whether classical histone deacetylases (HDAC1-11) are also involved in deacetylation of AcAPE1, we treated colon adenocarcinoma HCT116 cells with trichostatin A (TSA), a specific inhibitor for classical HDACs, and measured AcAPE1 level." (PMID 27655688, 2016).
cutaneous melanoma (2 papers, 2014 to 2021). A primary melanoma arising from atypical melanocytes in the skin.
developmental delay (2 papers, 2016 to 2024). "Previous studies show that down-regulation of HDAC1 leads to hyperacetylation of histone H4, which in turn results in developmental delay." (PMID 25672483, 2016). "The nucleosome remodeling and deacetylase (NuRD) complex, which includes proteins such as histone deacetylase 1 (HDAC1) and 2 (HDAC2), is another ATP-dependent chromatin remodeler complex whose impaired function leads to developmental delay, IDs, and ASDs, among other disorders." (PMID 39766920, 2024). "It is hypothesized that the ING2-induced developmental delay could be due to decreased expression of HDAC1 and concomitant increased expression of p21, and may not be associated with apoptosis because there was no increase in the expression of the pro-apoptotic Bax transcripts." (PMID 25672483, 2016).
ependymoma (2 papers, 2020 to 2023). A WHO grade II, slow growing tumor of children and young adults, usually located intraventricularly. "LSD1, HDAC1 and HDAC2 are all highly expressed across ependymoma groups, but HDAC1/2 transcription is even more pronounced in ZFTA ependymoma." (PMID 37085539, 2023). "Here, we have shown that both RCOR2 and LSD1 expression are essential in ZFTA ependymoma, but not or to a lesser extent in PFA ependymoma, and that ZFTA cells are sensitive to HDAC1/2 inhibitors in line with our previous observations." (PMID 37085539, 2023).
gallbladder cancer (2 papers, 2016 to 2023). "In order to further elucidate the effect of the ZFP64–HDAC1 axis on the NUMB–Notch1 signaling pathway, HDAC1 was overexpressed in gallbladder cancer cell lines with ZFP64 knockdown." (PMID 37760477, 2023). "However, the expression of HDAC1 in patients with gallbladder cancer is still unknown." (PMID 27092878, 2016).
head and neck squamous cell carcinoma (2 papers, 2021 to 2022). A squamous cell carcinoma that arises from any of the following anatomic sites: lip and oral cavity, nasal cavity, paranasal sinuses, pharynx, larynx, and salivary glands. "Similarly, histone deacetylase 1 (HDAC1) and microRNA-574-5p axis was found to repress CerS1 and alter C18 ceramide generation in head and neck squamous cell carcinoma (HNSCC), thereby allowing tumor growth and proliferation." (PMID 35565311, 2022).
Hodgkins lymphoma (2 papers, 2015 to 2021). A heterogeneous group of malignant lymphoid neoplasms of B-cell origin characterized histologically by the presence of Hodgkin and Reed-Sternberg (HRS) cells in the vast majority of cases. "Although HDAC1, 2 and 3 are all overexpressed in Hodgkin's lymphoma tissue samples, only high HDAC1 expression is correlated with a worse outcome." (PMID 26124919, 2015). "In Hodgkin's lymphoma, HDAC1, 2, and 3 are highly expressed, whereas low levels of HDAC1 may be a marker of worse outcomes." (PMID 34512154, 2021).
Insulin resistance (2 papers, 2020 to 2024). Increased resistance towards insulin, that is, diminished effectiveness of insulin in reducing blood glucose levels. "The data presented here suggest that treatment with MS-275 may help restore lipotoxicity-induced insulin resistance and inflammation in skeletal muscle via the inhibition of HDAC3, rather than HDAC1/2." (PMID 33362555, 2020).
invasive carcinoma (2 papers, 2008 to 2021). A carcinoma that is not confined to the epithelium, and has spread to the surrounding stroma. "Lesions of high-grade PIN in the vicinity of invasive carcinomas were identified in 56 (HDAC1), 57 (HDAC2) and 67 (HDAC3) cases, respectively." (PMID 18212746, 2008). "Expression of HDACs in high-grade PIN was almost identical with the strength of expression in the corresponding invasive carcinomas (HDAC1: r=0.961, P<0.001, HDAC2: r=0.756, P<0.001, HDAC3: r=0.694, P<0.001), indicating that HDAC overexpression is an early event in prostate carcinogenesis." (PMID 18212746, 2008).
leishmaniasis (2 papers, 2020 to 2022). Infectious disease that is transmitted through the bite of hematophagous female phlebotomine sand flies. "The present data not only demonstrate that up-regulation of HDAC1 and epigenetic silencing of host cell defense genes is essential for L. donovani infection but also provides novel therapeutic strategies against leishmaniasis." (PMID 32275661, 2020).
malaria (2 papers, 2015 to 2021). Malaria is a serious and sometimes fatal disease caused by a parasite that commonly infects a certain type of mosquito which feeds on humans. "These compounds are both hydroxymate-based inhibitors that target affect multiple stages of malaria parasites by inhibiting multiple HDACs, particularly HDAC1 (PF3D7_0925700) and HDA1 (PF3D7_147220)." (PMID 34268139, 2021).
mesothelioma (2 papers, 2015 to 2018). A usually malignant and aggressive neoplasm of the mesothelium which is often associated with exposure to asbestos. "Both HDAC1 and HDAC2 were expressed in the normal mesothelial MeT-5A cells, and HDAC1 was expressed at varying levels in the mesothelioma cell lines." (PMID 25970771, 2015). "As BAP1 depletion had a profound effect on the HDAC2/HDAC1 expression ratio in MSTO-211H cells, we next examined the relationship between endogenous HDAC2 and BAP1 mutation status in a panel of established mesothelioma cell lines." (PMID 25970771, 2015). "Indeed we find that HDAC2 appears more important than HDAC1 in maintaining viability of the BAP1 positive mesothelioma cell line MSTO-211H." (PMID 25970771, 2015).
metastatic carcinoma (2 papers, 2017 to 2025). A carcinoma which has spread from the original site of growth to another anatomic site. "The group reported that the expression of all potential substrates including HDAC1, Plk1 and Aurora A were higher in metastatic cancer cells than in normal cells." (PMID 29179506, 2017).
metastatic melanoma (2 papers, 2014 to 2016). A melanoma that has spread from its primary site to another anatomic site. "Altogether, the studies reported here indicate that the combination of ectopic p73 expression with knockdown of HDAC1 generates synergistically enhanced cytotoxicity in metastatic melanoma cells." (PMID 25071017, 2014).
mood disorder (2 papers, 2013 to 2021). A cognitive disorder a disturbance in which the person's mood is hypothesized to be the main underlying feature. "For instance, HDAC1 acts as a molecular switch between neuron survival and death and a regulator in mood disorders." (PMID 34638996, 2021). "To further investigate the mechanism of HDAC inhibition in the underpinnings and treatment of mood disorders, we identified from the literature Cpd-60 (Compound 19, also published as Compound 60), a benzamide-based, subclass selective inhibitor of HDAC1 and HDAC2." (PMID 23967191, 2013). "Our current findings stand as supportive evidence that selective inhibition of HDAC1 and HDAC2 results in beneficial changes in neuroplasticity and may be a novel target for mood disorder therapy." (PMID 23967191, 2013). "Together, this study demonstrates that selective inhibition of HDAC1 and HDAC2 in mice modulates transcription in mood circuits and alters relevant behaviors, and may be a viable mechanism for the development of clinical mood disorder treatments." (PMID 23967191, 2013).
myocardial infarction (2 papers, 2022 to 2024). Gross necrosis of the myocardium, as a result of interruption of the blood supply to the area, as in coronary thrombosis. "Inhibition of HDAC1 in cardiac endothelial cells and their exosomes promoted robust angiogenesis in vitro, as well as in a mouse model of myocardial infarction (MI)." (PMID 38427976, 2024). "And we employed a well-accepted myocardial infarction (MI) injury model and investigate on the role of HDAC1 in DUSP4/p38 pathway using HDAC1 siRNA in fibroblasts isolated from neonatal mice." (PMID 34236463, 2022).
parasite infection (2 papers, 2020 to 2022). "At an earlier time, 6 h post-infection, the expression of HDAC1 was significantly higher, suggesting the importance of the down-regulation of host innate defense genes during the preliminary establishment of the parasite infection." (PMID 32275661, 2020). "We next examined whether the expression levels of HDAC1 is altered in response to parasite infection." (PMID 32275661, 2020). "Taken together, these results suggest that parasite infection leads to reduced host H3 acetylation at CIITA pI and pIV with the help of HDAC1, leading to decreased CIITA transcription." (PMID 35433496, 2022).
Peritoneal Fibrosis (2 papers, 2018 to 2022). Disorder characterized by a wide range of structural changes in PERITONEUM, resulting from fibrogenic or inflammatory processes. "Except for HDAC6, another subtype of HDAC family, HDAC1 from class I has also been confirmed to be associated with peritoneal fibrosis." (PMID 35784347, 2022). "Overall, our study, pinpointing a role for HDAC1, revealed a new player in the regulation of peritoneal fibrosis, providing the rationale for future therapeutic opportunities." (PMID 29855565, 2018). "Thus, this research pinpointed a role for HDAC1 as a new player in the regulation of peritoneal fibrosis." (PMID 35784347, 2022).
prostate tumors (2 papers, 2008 to 2019). "The fact that HDAC1 expression correlated strongly with tumour dedifferentiation indicates a prominent role of this isoform in the control of prostate tumour differentiation." (PMID 18212746, 2008). "In addition, seven other genes, GGT1, HDAC1, KLK2, MYO6, PLA2G7, BICD1, and CACNAID, were found to be differentially expressed in prostate tumors of non-BCR and BCR patients." (PMID 31741711, 2019).
sinusitis (2 papers, 2017 to 2022). An acute or chronic inflammatory process affecting the mucous membranes of any sinus cavity. "The immunohistochemical results showed that HDAC1 was upregulated in the nasal epithelium of the sinusitis and NPs, and HDAC6 was upregulated in the sinusitis, whereas HDAC1 and HDAC6 were positive in the normal nuclei." (PMID 28883651, 2017). "In the present study, p63, ΔNp63, HDAC1 and HDAC6 were upregulated and CLDN-1 and -4 were downregulated in the epithelium of sinusitis and NPs." (PMID 28883651, 2017). "In the present study, HDAC1 was upregulated in the nasal epithelium of NPs, and HDAC6 was upregulated in sinusitis." (PMID 28883651, 2017). "We performed immunohistochemical analysis for HDAC1 and HDAC6 in normal, sinusitis and NP tissues." (PMID 28883651, 2017).
tauopathies (2 papers, 2018 to 2023). "Further studies in cellular and in tauopathy mouse models are needed to elucidate the precise competitive mechanisms causing the Tau-dependent reduction of the nuclear pool of HDAC1 and to identify the affected dementia-related genes that could induce or enhance the neuronal dysfunction and death." (PMID 37266450, 2023).
teratoma (2 papers, 2018 to 2020). A non-seminomatous germ cell tumor characterized by the presence of various tissues which correspond to the different germinal layers (endoderm, mesoderm, and ectoderm). "Importantly, immunoexpression of these HDACs was particularly high in cisplatin-exposed metastatic samples, with 10/14 (71.4%) and 13/14 (92.9%) tumors with strong immunoexpression of HDAC1 and HDAC2, respectively (including 4/6 and 6/6 of non-teratoma cases, specifically)." (PMID 33050470, 2020).